VWF (von Willebrand factor)
Diseases named in the same sentence as VWF in open-access papers (continued):
Sharing a sentence is not in itself a finding about the gene and the disease.
endothelial dysfunction (continued). "Endothelial dysfunction in COVID-19 induces a prothrombotic endothelial state, characterized by increased expression of tissue factor, von Willebrand factor, and impaired thrombomodulin and antithrombin activity, promoting coagulation activation and thrombus formation." (PMID 39359765, 2024). "The Increased release of the von Willebrand factor (vWf) in response to endothelial damage has led to the suggestion that vWf levels may serve as an indicator of endothelial dysfunction." (PMID 38337802, 2024). "vWF and collagen are unveiled on the subendothelial surface upon endothelial dysfunction." (PMID 39201390, 2024). "Moreover, elevated sodium can increase the production of von Willebrand factor by endothelial cells, another sign of endothelial dysfunction." (PMID 37884780, 2024). "This is the first study that showed lower levels of ADAMTS13 in LVNC patients, with a reduced ADAMTS13/vWF ratio, suggesting that endothelial dysfunction may play an important role in the pathogenesis of LVNC." (PMID 37297827, 2023). "Collectively, these studies provide evidence for the hypothesis that although vWF might serve as a marker of endothelial dysfunction consequent to an acute endothelial response to an ischaemic insult, it might not reflect any SVD-specific pathogenic effect." (PMID 37685924, 2023). "We determined associations between components of the classical (PRA-S, Ang I, Ang II) and alternative RAS (Ang 1–7) and parameters of liver disease severity (i.e. MELD), LSM, portal hypertension (i.e. HVPG), endothelial dysfunction (i.e. VWF antigen) and inflammation (i.e. IL-6)." (PMID 36653504, 2023). "Furthermore, the immunostained area for vWF, a marker of liver endothelial dysfunction, was increased in the eKO mice, as compared to that in the livers of WT mice." (PMID 37554269, 2023). "von Willebrand factor (VWF) is a marker of endothelial dysfunction and a prothrombotic protein central in primary hemostasis, including platelet adhesion, and secondary hemostasis, with formation of the VWF-factor VIII complex preventing rapid clearance of factor VIII." (PMID 37255854, 2023). "Furthermore, multiple weak correlations were found between several PCC symptoms and markers of endothelial dysfunction (ET-1 and VWF : Ag) and the inflammatory cytokine IL-1Ra." (PMID 37868959, 2023). "A retrospective study revealed that elevated levels of endothelial cell markers, such as von Willebrand factor (VWF) antigen and VWF propeptide, were observed in COVID-19 patients after an average of 68 days following infection, signifying sustained endothelial dysfunction in long COVID patients." (PMID 37907497, 2023). "In addition to impaired NO-dependent vasodilation, endothelial dysfunction is also manifested by increased production of pro-inflammatory, pro-adhesive and pro-thrombotic molecules, such as vWF, and PAI-1." (PMID 36984822, 2023). "ELISA results showed NETs from TBI patients, especially those with coagulopathy, could significantly impair endothelial dysfunction by decreasing the expression of syndecan-1, thrombomodulin, and VWF." (PMID 36802340, 2023). "Moreover, there were also positive correlations with systemic inflammation, vWF as a marker of endothelial dysfunction, and severity of hepatic dysfunction and portal hypertension." (PMID 36873421, 2023). "However, von Willebrand factor (vWF), which is also a key molecule for platelet aggregation after tissue injury, was lower in intact vessels of GK rats, suggesting a possible endothelial dysfunction at baseline." (PMID 37519334, 2023). "Consistent findings contributing to the hypercoagulability include elevated von Willebrand factor secondary to endothelial dysfunction; elevated fibrinogen and FVIII, both acute‐phase proteins; reduced thrombomodulin; and reduced ADAMTS‐13 with altered von Willebrand factor/ADAMTS‐13 ratio." (PMID 35733235, 2022). "vWF, a multimeric plasma glycoprotein, acts as a marker of endothelial dysfunction." (PMID 35342404, 2022).
endothelial dysfunction (continued). "In the current study, however, considering that the extracts reduced the inflammatory response in ECFCs, the increased expression of vWF should not be associated with endothelial dysfunction, but with greater maturation of these cells." (PMID 35624715, 2022). "Von Willebrand factor (vWF) is considered a more conventional marker of endothelial dysfunction." (PMID 36005129, 2022). "Considering the predominantly endothelial source of VWF in the bloodstream, higher VWF:Ag levels in patients with CAD may be associated with characteristic endothelial dysfunction and endothelial damage." (PMID 36531725, 2022). "Additionally, increased plasma VWF levels are an indicator of endothelial dysfunction, as the vascular endothelium is involved in the VWF production." (PMID 35482749, 2022). "Furthermore, endothelial dysfunction fosters platelet adhesion to von Willebrand factor (vWF) and consequential platelet activation by the release of paracrine mediators, such as adenosine diphosphate (ADP) and thromboxane (TxA2)." (PMID 36233252, 2022). "Therefore, we sought to explore the relationship between markers of platelet activation (sP-selectin), endothelial dysfunction (vWF) and platelet count." (PMID 35250627, 2022). "The von Willebrand factor is a plasma glycoprotein that is primarily active in the coagulation process, through a process in the vascular endothelium, but also an indicator of endothelial dysfunction." (PMID 35381849, 2022). "Therefore, markers of endothelial proinflammatory activation including the cell surface expression of adhesion molecules like VCAM-1 and prothrombotic mediators like vWF are important signs of endothelial dysfunction." (PMID 35906216, 2022). "Since OPG is a regulatory molecule related to arterial stiffness, VWF correlations with Cys C are significant and may characterize endothelial dysfunction." (PMID 35453881, 2022). "Another way to evaluate endothelial dysfunction in humans is the measurement of certain “classical” indicators, for example the pro-coagulant von Willebrand Factor (vWF) or by the evaluation of endothelial-dependent dilatation or ischemia-induced flow-mediated dilatation." (PMID 34440201, 2021). "The finding of higher concentrations of vWF : Ag in hyperthyroid cats suggests endothelial dysfunction and could result in thrombosis." (PMID 34590754, 2021). "Taken together, endothelial dysfunction (elevated vWF level), with the release of fibrinolysis inhibitor PAI-1, and hyperimmune response (increased ESR, CRP, ferritin, and IL-6) with younger (higher H-IPF) activated platelets seem to be significant contributors to thrombogenesis in COVID-19." (PMID 34940584, 2021). "Furthermore, acute insulin-induced hypoglycemia has been demonstrated to increase vWF levels in humans, likely the consequence of the hypoglycemia-induced increase in corticosterone levels or endothelial dysfunction, and enhancing platelet aggregation." (PMID 34091064, 2021). "Interestingly, incubation of HAoECs with spike protein caused reduced expression of transcription factor KLF2, and increased expression of the pro-coagulant, vWF, consistent with induction of endothelial dysfunction." (PMID 34935423, 2021). "The roles of VWF in endothelial dysfunction and inflammation in COPD have been demonstrated." (PMID 34479474, 2021). "The changes in KLF2 and vWF expression are indicative of endothelial dysfunction and may perpetuate vascular inflammation and coagulation." (PMID 34935423, 2021). "Another study found a significantly elevated level of VWF in patients with COVID-19 that lend credence to the SARS-CoV-2-induced endothelial dysfunction hypothesis." (PMID 34012410, 2021). "Elevated levels of factor VIII and VWF might reflect the involvement of endothelial dysfunction in a hypercoagulable state because these factors are produced predominantly in endothelial cells." (PMID 34769508, 2021).
endothelial dysfunction (continued). "Finally, endothelial dysfunction results in the massive release of von-Willebrand factor (VWF) from Weibel-Palade bodies, which has been reported in COVID-19." (PMID 34064553, 2021). "However, previous observations that BDNF preserves from endothelial dysfunction and that low BDNF levels are associated with high von Willebrand Factor levels, support the re-equilibrating effect as more likely." (PMID 34205863, 2021). "In addition, vWF has been regarded as a prospective biomarker for the diagnosis of endothelial dysfunction." (PMID 33107067, 2021). "The present study defines VWF/ADAMTS13 axis parameters as markers of endothelial dysfunction, along with thrombin and plasmin generation as predictors of thrombosis and fibrinolysis, based on two important risk factors known to predict poor outcome in COVID-19 infection: increased age and obesity." (PMID 35087853, 2021). "Endothelial dysfunction is suggested to be involved in the progression of COVID-19 because of the atypical manifestations among patients such as cardiac injury and hypercoagulability as measured by an increase in D-dimer and von Willebrand factor (VWF) levels." (PMID 34012410, 2021). "Hyperthyroid cats could have endothelial dysfunction as indicated by increased vWF : Ag which could potentiate thrombogenesis." (PMID 34590754, 2021). "A disarray in the coagulation and the fibrinolytic system due to myocardial injury has been observed as increased D-dimer (thrombogenesis indicator), fibrinogen (coagulation factor), vWF (endothelial dysfunction marker) and CD41 level (platelet and megakaryocyte surface marker)." (PMID 34882718, 2021). "The pathogenetic mechanisms may include endothelial dysfunction, increased consumption of platelets and the decreased production of platelets, von Willebrand factor elevation, Toll-like receptor activation, and tissue-factor pathway activation." (PMID 33602949, 2021). "Circulating biomarkers such as endothelin-1, E- and P-selectins, vWF and soluble adhesion molecules that signify endothelial dysfunction may appear as early biomarkers of viral infection and probable organ dysfunction." (PMID 32848893, 2020). "With respect to circulating biomarkers, depression-linked type-D personality, that is, the combination of negative affectivity and social inhibition, has already been associated with endothelial dysfunction assessed by soluble ICAM-1 and VCAM-1, E-selectin, and VWF." (PMID 32230840, 2020). "For this purpose, serotonin and thromboxane A2 (TXA2) plasma levels were assessed as markers of platelet activation, von Willebrand antigen (VWF:Ag) and activity (VWF:Ac) as markers of endothelial dysfunction and soluble p-selectin as a marker of both platelet activation and endothelial injury." (PMID 32992591, 2020). "Taking into consideration that vWF is predominantly secreted by the endothelium, elevated plasma vWF might be considered to be a marker of endothelial dysfunction." (PMID 33096906, 2020). "Our group has also reported signs of less endothelial dysfunction otherwise accompanying ageing, due to the intervention with selenium and coenzyme Q10, as seen from evaluation of the von Willebrand factor, and the plasminogen activator inhibitor-1 and the increase in IGF-1." (PMID 33317156, 2020). "Serum magnesium was inversely associated with many CVD risk factors including prevalent atrial fibrillation, lung function (FEV1) and markers of inflammation (IL-6), endothelial dysfunction (vWF) and cardiac dysfunction [NT-proBNP and cardiac troponin T (cTnT)]." (PMID 29663176, 2018). "We have observed an inverse relationship between circulating serum magnesium and vWF (a marker of endothelial dysfunction) and IL-6 (a pro-inflammatory cytokine and a marker of inflammation) after taking BMI into account, in line with other populations studies." (PMID 29663176, 2018).
endothelial dysfunction (continued). "Elevated levels of VWF have been associated with an increased risk of type 2 diabetes which has been attributed primarily to the role of VWF as a marker of endothelial dysfunction rather than to its role in thrombosis." (PMID 27787621, 2017). "Von Willebrand factor (vWF) is a biomarker of endothelial dysfunction." (PMID 28134282, 2017). "Upon endothelial dysfunction, cells release more vWF, which is a marker of endothelial dysfunction." (PMID 28057038, 2017). "Our findings reveal a new role of vWF in preventing of Ang II-induced endothelial dysfunction." (PMID 27443965, 2016). "In addition, FVIII and vWF are well known to be involved in endothelial dysfunction that is a key process in the pathogenesis of PAH." (PMID 27886187, 2016). "In addition, simvastatin significantly attenuated the development of acute endothelial dysfunction both at 2 and 24 h of reperfusion as evidenced by improved vasodilation in response to Ach and reduced sinusoidal vWF expression." (PMID 26905693, 2016). "Unraveling how endothelial vWF prevents the onset of endothelial dysfunction could provide new avenues for protection against Ang II-induced cardiovascular injury." (PMID 27443965, 2016). "Copeptin was strongly associated with heart rate (a marker of increased sympathetic nervous system) and was also strongly correlated with CRP (inflammation) and vWF (a marker of endothelial dysfunction), factors shown to be related to insulin resistance and diabetes." (PMID 26158609, 2015). "At baseline, dp-ucMGP and dp-cMGP correlated significantly with the inflammation marker IL-6 (r 0·321 and r 0·308, respectively; P < 0·05) and with markers of endothelial dysfunction von Willebrand factor (r 0·395 and r 0·393; P < 0·01) and VCAM (r 0·399 and r 0·653; P < 0·001)." (PMID 26495126, 2015). "vWF is an important parameter reflecting endothelial dysfunction and blood coagulation activation." (PMID 26539516, 2015). "Increased D-Dimer levels in patients with renal dysfunction may result from endothelial dysfunction, since release of VWF promotes platelet adhesion and aggregation and, thus, microthrombi formation." (PMID 26168189, 2015). "This questions the suitability of vWF levels as a marker for endothelial dysfunction at an early disease state and indicates that, at the early onset of hypertension, vWF is not a target of LC n-3 PUFAs to mediate their cardioprotective effects at the concentration and duration used in this study." (PMID 26290867, 2015). "With regard to markers of endothelial dysfunction/activation, plasma levels of vWf, sVCAM-1, MCP-1, and PTX3 were significantly increased in RA patients, whereas differences in the concentrations of sE-selectin were weakened after the standardization of the results to gender and age." (PMID 24864133, 2014). "The stage of CKD does not influence levels of cfDNA; however, there is a correlation with levels of hsCRP and vWF, but not other inflammatory cytokines associated with endothelial dysfunction." (PMID 25371664, 2014). "von Willebrand factor (vWF) is a marker for endothelial dysfunction and mediates platelet adhesion." (PMID 24688225, 2014). "Furthermore, catheter ablation demonstrated effects on pro-coagulant state and endothelial dysfunction, with increased concentrations of tissue plasminogen activator and von Willebrand factor (vWF, implying endothelial damage) at 24 h after procedure." (PMID 25390649, 2014). "However, in our study we observed positive correlation between vWF, a marker of endothelial dysfunction, and levels of TC and LDL-C." (PMID 24864133, 2014). "Regarding endothelial dysfunction (ED), vWF, ICAM-1, and VCAM-1 were selected as indicators." (PMID 23671885, 2013). "Hence, increased deposition of vWF, a marker of endothelial dysfunction, is seen in the irradiated heart." (PMID 23894340, 2013).
endothelial dysfunction (continued). "Characterizing the evolution of sPsel and VWF levels in trauma patients may help to understand the roles of platelet activation and endothelial dysfunction in trauma and TIC." (PMID 24034700, 2013). "Similarly, higher AF was detected in patients with endothelial dysfunction expressed by vWF, ICAM-1, and VCAM-1." (PMID 23671885, 2013). "Indeed markers of endothelial dysfunction such as sICAM-1, von Willebrand factor and plasminogen activator inhibitor type 1 (PAI-1) are elevated in AMD patients and are related to formation of drusen and choroidal neovascularization (CNV)." (PMID 23596508, 2013). "In patients with ACS, von Willebrand factor (vWF) levels are raised at admission, which may reflect endothelial dysfunction/damage." (PMID 19690647, 2007). "Notably, VWF is considered to be a marker of endothelial dysfunction." (PMID 40362344, 2025). "Furthermore, fT3 correlated with parameters of PH (HVPG: ρ = -0.300; p <0.001), endothelial dysfunction (von Willebrand factor antigen [VWF]: ρ = -0.357; p <0.001), and hyperdynamic circulation (pro-brain-type natriuretic peptide [proBNP]: ρ = -0.385; p <0.001)." (PMID 38125301, 2024). "For instance, ADAMTS13 deficiency has been observed in severe malaria, particularly in cerebral manifestations, which may contribute to the pathophysiology of complicated malaria by impairing the regulation of von Willebrand factor (VWF) and promoting endothelial dysfunction." (PMID 37638001, 2023). "Moreover, FMD% correlated negatively and significantly with vWF that remained significant after regression analysis suggesting that endothelial dysfunction and endothelial activation are closely related to each other with established endothelial cell abnormalities in those children with GD." (PMID 37022495, 2023). "Although von Willebrand factor (vWF), a well-known HFpEF biomarker linked to endothelial dysfunction, did not present with a substantial perturbation, it was a unique protein differentiated between acute HFpEF and chronic HFpEF (log2FC = 2.19, FDR = 3.54 × 10−3)." (PMID 36291628, 2022). "It has been observed that this marker is associated with increased fibrinogen transcapillary escape rate and increased von Willebrand factor levels in diabetic patients with reduced eGFR, suggesting that decreased eGFR may reflect general endothelial dysfunction and systemic vascular injury." (PMID 35272683, 2022). "Finally, we found that BAFF influences augmented serum vWF—an early endothelial dysfunction marker." (PMID 35629302, 2022). "Moreover, the inhibition of vascular remodeling may have alleviated endothelial dysfunction and reduced the expression of vWF immunostaining upon CBD treatment." (PMID 34832902, 2021). "Moreover, vWF is also regarded as a promising biomarker for endothelial dysfunction." (PMID 33107067, 2021). "As endothelial dysfunction may trigger inflammation and is closely linked with vascular pathology, including peripheral vascular calcification, we investigated normal (CD31, CD105, vWF) and activated (ICAM‐1) endothelial markers." (PMID 30868685, 2019). "Furthermore, it is suggested that endothelial dysfunction due to the increased vWF activity may be related to the progress of acute leukemia." (PMID 30626079, 2019). "Whether circulating BDNF levels are associated with von Willebrand factor (vWF) levels, which are indicators of endothelial dysfunction is not known." (PMID 29409455, 2018). "Endothelial dysfunction may be assessed using changes in circulating markers, such as plasma von Willebrand factor (vWF), which indicate endothelial damage because these markers are primarily produced by endothelial cells to facilitate platelet adhesion and aggregation at sites of injury." (PMID 29409455, 2018).